PIGR (polymeric immunoglobulin receptor)
Diseases named in the same sentence as PIGR in open-access papers (continued):
Sharing a sentence is not in itself a finding about the gene and the disease.
infection (continued). "We next sought to determine whether after infection the pIgR would increase along with increased sIgT levels observed in the SB mucus." (PMID 35379790, 2022). "In short, the studies showed that pIgR-/- naïve mice i.e. lacking secretory antibodies were at significantly greater risk of infection than naïve BL/6 naïve mice." (PMID 36618388, 2022). "For example, mice lacking the pIgR are more susceptible to Mycobacterium bovis strain BCG than normal mice in an infection model considered to be largely CD4+ T cell-dependent." (PMID 36618388, 2022). "PIGR was generally known as a mediator of transcytosis of polymeric immunoglobulins, accelerating the secretion of IgA and IgM and comprising the defense line against infection." (PMID 33937393, 2021). "In addition, PIGR mRNA was significantly higher in chronic HCV-infection than that in resolver in GSE93711 (p < 0.05)." (PMID 33937393, 2021). "An in vivo model of chronic lung infection by Pseudomonas aeruginosa-coated microbeads showed that infection could restore pIgR expression and IgA production in the lungs of F508del mice through an IL-17 inflammatory host response." (PMID 34944110, 2021). "pIgR deficient mice had enhanced levels of the anti-viral cytokine IFN-γ, which might explain the reduced infection rates." (PMID 30984170, 2019). "Although the cause of this behavior was not determined, the results support the question of whether a similar mucosal epithelium colonizing pathogen, such as EHEC also has the potential to use pIgR for adherence during infection." (PMID 31188867, 2019). "It is possible that an epithelium that is sufficiently efficient to allow the transcytosis across epithelial cells of IgM with high to moderate avidity to the HIV-1 envelope and that the pIgR may protect against infection." (PMID 29977063, 2018). "Specifically, EBV:EBV-specific SIgA immune complexes bind to pIgR on non-susceptible epithelial cells and are internalized to initiate infections in vitro." (PMID 29751532, 2018). "Alterations to the immune baseline of the pIgR KO mice may also be beneficial or detrimental during infection." (PMID 29751532, 2018). "Notably, in all brain compartments at all time points after infection, more than 95% of pneumococci co-localized with pIgR expressed on the vascular endothelium." (PMID 24841255, 2014). "Infection and inflammation are known to upregulate pIgR in the mammary gland via interferon γ, so we asked whether the increase in rotavirus-specific IgA in stool after pup vaccination could be attributed to live vaccine transmission to dams and a subsequent increase in total milk IgA." (PMID 41087582, 2025). "Infection induced the expression of cytokine and chemokine genes involved in chemotaxis, cell recruitment, and Th1/Th17 responses, as well as genes coding for membrane receptors, including Fc receptors, pIgR, and mucosal homing receptors, B-cell receptor signaling and antibody formation." (PMID 30692990, 2018). "However, this IgA may not have possessed the necessary secretory component required by the polyclonal immunoglobulin receptor (pIgR) to transcytose IgA into the lumen to neutralize the infection in vivo, by preventing microbial attachment." (PMID 23613984, 2013). "Compared with the HLH-malignancy group, three DEPs were significantly decreased in the HLH-other infection group, including CD32 (FCGR2A), CD163, and polymeric immunoglobulin receptor (PIGR)." (PMID 37653176, 2023). "In this study, increased intestinal pIgR expression here may mean more mucosal secretory IgA antibody production in the gut, which help in reducing cecal Salmonella load and facilitating Salmonella elimination from the gut lumen during the recovery phase of infection." (PMID 36221113, 2022).
infection (continued). "Studies in naive mice lacking the pIgR suggest that polyspecific sIgA may afford some protection against infection, but the efficiency of many pathogenic viral and bacterial ‘invasion’ systems would suggest that this polyspecific antibody is insufficient to stop overt pathogen entry." (PMID 36618388, 2022). "In addition, PDCoV might reduce the ability of FcRn and pIgR to transport PDCoV-specific IgG and IgA across the mucosal epithelium, resulting in impaired intestinal immunity in the mucosa, reducing the host’s anti-infection ability." (PMID 31936476, 2020). "To assess the systemic spread of S. Typhimurium in pIgR KO compared to C57BL/6, we orally gavaged mice with S. Typhimurium and sacrificed mice at 7 days post-infection to collect tissues for evaluation of bacterial growth." (PMID 29856838, 2018). "In M. japonicus, WSSV interacts with a soluble C-type lectin (CTL) through the VP28 protein to promote its infection, whereas the binding of WSSV envelope protein VP24 to the polymeric immunoglobulin receptor (pIgR) facilitates viral entry via the pIgR-CaM-clathrin-mediated endocytic pathway." (PMID 39964166, 2025). "IgA and sIgA have been shown to be important in protection against pneumococcal colonization since pIgR−/− mice, which lack the ability to secrete IgA to the mucosal lumen, were not protected like wild-type mice against infection by serotype 14 S." (PMID 40852712, 2025). "Our BL/6 pIgR-/- mouse was developed to study the role of sIgA in infection immunity, particularly to the Gram negative enteric pathogen Salmonella enterica var Typhimurium, which is subject to growth control in the B129 mouse by Nramp1." (PMID 36618388, 2022). "The pIgR KO mice showed an increased median survival (P<0.05 by the log-rank Mantel-Cox test) as compared to the C57BL/6 mice (undefined for pIgR KO mice and 9 days for C57BL/6 mice), with 55% of pIgR KO mice and 27% of C57BL/6 mice alive at 16 days post infection." (PMID 29856838, 2018). "The ability of EBV immune complexes to be translocated from the basal to the apical side without infection was confirmed in vitro in polarized pIgR-expressing MDCK cells." (PMID 29751532, 2018).
bacterial infection (9 papers, 2014 to 2025). "Recently, several studies showed that PIgR is one of the pattern recognition receptors (PRRs) which are expressed and activated through the MECs to respond to bacterial infection and so-called pathogen-associated molecular patterns (PAMP)." (PMID 33260718, 2020). "In other teleost species, high pIgR expression was found in gills after bacterial infection was induced." (PMID 35887127, 2022). "PIGR is widely expressed in the mucosal epithelium and can be upregulated by inflammatory cytokines during viral or bacterial infection." (PMID 35992840, 2022). "Thus, together with previous studies, our results strongly suggest an important role of pIgR in the transport of Igs into the buccal mucus in both mammals and teleosts after bacterial infection." (PMID 33072100, 2020). "Several studies addressed the role of pIgR in the pathogenesis of bacterial disease." (PMID 28694492, 2017). "Interestingly, the presence of IgA producing plasmablast cells in all three biopsy samples and the epithelial cell expression of PIGR, that is involved in the dimeric IgA transcytosis, rekindles the role of secretory IgA in the defense against bacterial infections in the kidney." (PMID 35657798, 2022). "However, the contribution of pIgR to the bacterial infection is unclear." (PMID 33072100, 2020). "Since AT2 do not express endogenous pIgR under physiological conditions or after bacterial infection, the emergence of pIgR immunoreactivity likely results from a binding of extracellular pIgR." (PMID 40642082, 2025).
adenocarcinoma (7 papers, 2014 to 2025). A common cancer characterized by the presence of malignant glandular cells. "High PIGR expression independently predicts a decreased risk of recurrence and improved survival in patients with adenocarcinoma of the upper gastrointestinal tract." (PMID 40386563, 2025). "High PIGR expression independently predicts a decreased risk of recurrence and an improved survival in patients with adenocarcinoma of the upper gastrointestinal tract." (PMID 24694107, 2014). "High PIGR expression is associated with a less advanced T-stage and independently predicts a decreased risk of recurrence and an improved survival in patients with adenocarcinoma of the upper gastrointestinal tract." (PMID 24694107, 2014). "Parallel to that, 5 proteins were expressed lower in SOL adenocarcinomas and the low expression of which was correlated with poor OS, including PIGR, CHDH, NAPSA, PLEKHA7 and SELENBP1." (PMID 38182978, 2024). "In the present study, we examined the expression, clinicopathological correlates and prognostic significance of PIGR expression in an extended cohort of adenocarcinoma of the upper gastrointestinal tract." (PMID 24694107, 2014). "The results from this study demonstrate that high PIGR expression is an independent favourable prognostic factor in adenocarcinoma of the upper gastrointestinal tract." (PMID 24694107, 2014). "The aim of this study was to examine the expression and prognostic impact of PIGR in a consecutive cohort of adenocarcinoma of the esophagus, GEJ and stomach (n = 173)." (PMID 24694107, 2014). "PIGR-negative adenocarcinomas in the distal oesophagus and gastroesophageal junction have been found to be more aggressive and to possess higher metastatic potential compared to adenocarcinomas with high expression of PIGR." (PMID 24568264, 2014).
cardiovascular disease (2 papers, 2020 to 2022). "The study discovered the correlation between 23 pIgR peptides with eGFR and cardiovascular disease and provides insights into pIgR cleavage." (PMID 34538010, 2022).
infectious disease (2 papers, 2024 to 2025). A disorder directly resulting from the presence and activity of a microbial, viral, or parasitic agent in humans. "Together with previous studies, these findings raise the possibility that plasma pIgR, together with pIgs, plays a pro-pathogenic role in a broad range of infectious diseases." (PMID 40642082, 2025). "Nevertheless, these studies raise the possibility that plasma pIgR is involved in the pathogenesis of infectious diseases caused by various pathogens." (PMID 40642082, 2025). "Previous studies have focused on pIgR in the mucus and pIgR-expressing cells, little is known about the functional significance of plasma pIgR in infectious diseases." (PMID 40642082, 2025). "Previous reports of the function of pIgR in infectious diseases have been contradictory." (PMID 40642082, 2025). "There has been no report on the role of pIgR-IgM immune complexes in infectious diseases." (PMID 40642082, 2025).
kidney disease (2 papers, 2020 to 2024). "After the investigation of the association of the pIgR-peptides with the eGFR in the full cohort, we also investigated their mean amplitude in different kidney disease etiologies." (PMID 32427855, 2020).
inflammation (1 paper, 2017). Aberrant reaction of the microcirculation characterized by movement of fluid and leukocytes from the blood into extravascular tissues. "An association of elevated epithelial pIgR expression and lung inflammation was also observed by others." (PMID 28694492, 2017).
respiratory diseases (1 paper, 2025). "However, the control group of this study were subjects with no respiratory disease and, therefore, it is not clear whether the elevation of plasma pIgR also occurs in subjects with non-ARDS, respiratory diseases." (PMID 40642082, 2025).
PIGR also shares sentences with these, for which no sentence is quoted: Barrett esophagus (4 papers); gastric adenocarcinoma (4); dysplasia (3); lung adenocarcinoma (3); gastric tumors (2); immune disorders (2); non-alcoholic fatty liver disease (2); rectal cancer (2); abdominal aortic aneurysm (1); acute coronary syndrome (1); acute respiratory distress syndrome (1); autosomal dominant polycystic kidney disease (1); carcinosarcoma (1); Chronic Fatigue Syndrome (1); cystic fibrosis (1); cystitis (1); dry eye (1); endometriosis (1); endothelial dysfunction (1); epithelial neoplasm (1); esophageal squamous cell carcinoma (1); gastrointestinal tumors (1); glaucoma (1); gynecological cancer (1); hepatitis C virus (1); Hypertension (1); Immunodeficiency (1); Intestinal Diseases (1); laryngeal squamous cell carcinoma (1); lung diseases (1).
A further 13 diseases each share a sentence with PIGR in 1 paper.